MYC (MYC proto-oncogene, bHLH transcription factor)
Diseases named in the same sentence as MYC in open-access papers (continued):
Sharing a sentence is not in itself a finding about the gene and the disease.
tumor (continued). "Thus, mRNA m6A modification results in opposite outcomes of MYC RNA transcripts, stabilization or degradation, in different tumor types, probably due to distinct reader proteins that induce variable consequences." (PMID 37192910, 2023). "Therefore, it is possible for the activation of MYC-degrading ubiquitin ligases to interfere with MYC stability, in particular, because the MYC oncoprotein is expressed above physiological levels in MYC-dependent tumor cells." (PMID 36969025, 2023). "SNHG3/c‐MYC/BMI1 axis may be a novel target for regulating tumor growth and metastasis in BLCa patients." (PMID 36208024, 2023). "Most tumour types show deregulated expression of MYC owing to direct alterations of the locus (for example, gene amplification or translocation) or from the activation of upstream signalling pathways (Wnt, Notch and so on), resulting in MYC-driven oncogenic transformation." (PMID 37407816, 2023). "Notably, these cells express high levels of p-ERK1/2 compared to c-MYC tumor-derived cell lines (HCC3 and HCC4)." (PMID 37500626, 2023). "In a study on the association between tumor grade and LLPS-related genes, the LLPS-related genes E2F and MYC may be important determinants of survival in high-risk groups." (PMID 37953920, 2023). "Besides its effects on intrinsic tumor cell biology, hyperactivation of MYC leads to alterations in the tumor immune microenvironment (TME) in multiple cancers." (PMID 37279073, 2023). "We also report the downregulation of the tumor suppressor miR-150, a regulator of MYC." (PMID 37711209, 2023). "At the molecular level, the juxtaposition of HNRNPH1 and SOX11 super-enhancers to MYC cis-regulatory elements, through a mechanism of distance looping, appears to be responsible for MYC overexpression and the abnormal proliferation of group 3 tumor cells." (PMID 37568705, 2023). "Indeed, reduced in vitro infection and viral spread, as well as delayed tumor activation in a MYC/Runx2 mouse model using replication-competent recombinant MuLV lacking a functional (i.e., BET protein-binding) ET domain-binding motif, have been reported." (PMID 37766260, 2023). "We examined whether GW7647 or Simvastatin treatment reduced tumor growth via inhibition of MYC protein expression." (PMID 37117191, 2023). "Overall, MYC showed a trend of increased frequency of positive expression in recurrent/metastatic FN RMS, and YBX1 was expressed in all primary and metastatic FN and FP RMS tumor tissue samples examined, suggesting that MYC and YBX1 play a role in both primary and recurrent/metastatic RMS tumors." (PMID 37345125, 2023). "Interestingly, it has been found that eccDNA amplification in genes like EGFR, c-MYC, and RAB3B, which are associated with autophagy, can intensify the "stemness" of tumor cells." (PMID 39534571, 2023). "They found that MLN4924 treatment caused c-MYC accumulation in wild-type cells, tested the response of isogenic lines to MLN4924 and found that MLN49244 could still stimulate tumor sphere formation in FBXW7 empty cells." (PMID 36983561, 2023). "Therefore, many in vitro and in vivo experiments have proved that modifying or stabilizing G4 structures in promoter regions will reduce the expression of tumor-causing genes, such as VEGF, KRAS, BCL2, and MYC." (PMID 37323535, 2023). "The tumor was characterized by a MYC amplification, CD31 and ERG immunohistochemical positivity and was further characterized by using next generation sequencing (TruSight Oncology 500) in combination with the R-package XenofilteR to separate mouse from human sequence reads." (PMID 36788310, 2023). "TCGA data show that MYC amplification accounts for 21% of all tumor samples." (PMID 36959802, 2023). "Indeed, several observations indicate that MYC regulates transcription of specific gene subsets that concomitantly favour tumour progression and evasion of cell death pathways." (PMID 37599362, 2023).
tumor (continued). "However, B cells lacking surface BCR (Ig-) were overrepresented in the secondary lymphoid organs of pre-tumor stage λ-MYC mice." (PMID 37809061, 2023). "Therefore, the survival covariance of all sialyltransferases and MYC expression was compared across all tumor types in PRECOG." (PMID 36897988, 2023). "Moreover, FAT4 expression was negatively correlated with DNA repair, MYC targets, G2M checkpoint, DNA replication, reactive oxygen species-upregulated genes, cellular response to hypoxia, and tumor proliferation signature." (PMID 37735184, 2023). "In such cases, MYC and HIF1α may cooperatively tailor a gene expression program that takes advantage of the pro-tumorigenic aspect of each protein to fuel tumor growth." (PMID 37601651, 2023). "Expression of MYC was significantly higher in tumor tissues than in non-tumor tissues (p < 0.001)." (PMID 37117191, 2023). "We also found a novel potential tumor suppressor gene NLRP6, which may negatively regulate the E2F and MYC pathways and be associated with higher immune cell infiltration levels, which lead to better prognosis." (PMID 35651286, 2023). "Interestingly, HIRA loss in Fh1-deficient cells leads to tumour initiation and growth in the kidney capsule and activates oncogenic transcriptional programs such as EMT, E2F and the proto-oncogene MYC signatures." (PMID 37689804, 2023). "Furthermore, when mice treated with T/CQ were fed Dox chow to induce c-MYC expression in tumors that had initially responded to T/CQ treatment, tumor regrowth was observed, suggesting that c-MYC expression can mediate acquired T/HCQ resistance." (PMID 36719686, 2023). "Notably, the signaling of NO triggers the activity of PI3K/Akt-dependent c-MYC and finally induces tumor cell proliferation." (PMID 37895941, 2023). "For example, electroporation-loading of MYC oncogene-targeting sgRNA/Cas9 plasmids into CD19-chimeric-antigen receptor-modified HEK293T cells produced EVs results in a higher distribution in CD19 positive tumour tissues and more effective MYC genome editing than that of plain EVs." (PMID 37291577, 2023). "The decrease of SOX2 or MYC in HNSCC by hDT806 was parallel to hDT806's stimulation of the tumor-intrinsic STING pathway, indicating there could be a crosstalk between these transcription factors and STING signaling that warrants further study." (PMID 37898690, 2023). "Furthermore, MYC contributes to immune evasion in tumor cells by inducing the expression of PD-L1, which suppresses the attack from immune cells against the cancer cells." (PMID 37755397, 2023). "E2F and MYC played a vital role in the proliferation of tumor cells." (PMID 36631756, 2023). "In addition, the development of fluorescent probes with high specificity and affinity to detect MYC G4 elements will become an important experimental tool for the study of MYC tumor therapy." (PMID 36966168, 2023). "However, the functional relationship between MYC and MondoA is tumor type-specific and influenced by altered MYC levels." (PMID 37443779, 2023). "In NB, c-MYC target genes were significantly upregulated in neoplastic tumor clusters obtained from different datasets, while MYCN targets were significantly upregulated in tumor clusters from the 10x sequenced dataset (Fisher Exact Test, one-tail, FDR < 0.05)." (PMID 37760568, 2023). "Consequently, antibody-loaded micelles efficiently suppressed c-MYC in tumor tissue, thereby inhibiting tumor growth." (PMID 37190185, 2023).
tumor (continued). "Consequently, treatment with 10058-F4 reversed c-MYC- and miR-150-dependent autophagy defects and induced cytotoxicity and tumor reduction in NSCLC in vitro and in vivo." (PMID 37111592, 2023). "However, amplification of MYC alone is insufficient for tumor development in vivo; co-amplification of the PVT1 gene downstream of the MYC gene is required." (PMID 36831498, 2023). "Similarly, the relative tumor area was larger in hep-c-MYC/AR-V7 mice than hep-c-MYC mice in both sexes." (PMID 36746917, 2023). "However, tumor relapse under metformin treatment cannot be excluded since CSCs can acquire resistance mainly due to MYC overexpression, promoting a Warburg-like glycolytic phenotype." (PMID 37538108, 2023). "Interestingly, FH-associated tumorigenesis is enhanced by the activation of well-known proto-oncogenes, such as MYC, and suppression of tumour suppressors, including PTEN." (PMID 37689804, 2023). "However, alisertib plus T/CQ elicited tumor regression, suggesting that reducing the c-MYC expression by AURKA blockade conferred sensitivity to T/CQ therapy." (PMID 36719686, 2023). "Indeed, patient tumor samples with low IL-11Rα expression also displayed low levels of c-MYC gene expression while samples with high IL-11Rα expression correlated with levels of c-MYC gene expression." (PMID 36834778, 2023). "Numerous studies have identified MYC target genes in a variety of tumor cells." (PMID 37342196, 2023). "Therefore, the TIC tumor sections likely had preferential MSI2-dependent increase of MYC translation." (PMID 37117191, 2023). "High-risk group was enriched in aggressive molecular changes such as DNA repair, E2F target, G2M checkpoint, and MYC targets, which might drive rapid proliferative rate and promote tumor progression." (PMID 36918943, 2023). "Furthermore, miR-1827 reduced tumor development by decreasing MYC and FAM83F levels in in vivo tests." (PMID 37986065, 2023). "MYC can reshape the tumor microenvironment, evading host immune responses." (PMID 37799727, 2023). "Additionally, it has been reported that the protein encoded by MXI1 is a transcriptional repressor thought to negatively regulate MYC function 62, and is therefore a potential tumor suppressor." (PMID 37441593, 2023). "Moreover, loss of 14q induced the upregulation of MYC signaling, N-glycosylation, and the IFN-γ signaling pathway in tumor cells, and was identified in 75% of CIMP+ tumors." (PMID 37533434, 2023). "According to the results of genomic differences between primary tumor and post-LM CSF, we speculated that MYC and CCNE1 amplification may be closely related to LM." (PMID 37131253, 2023). "MYC is a hub-gene in cancer progression by controlling almost every aspect of tumour malignancy." (PMID 37667197, 2023). "In the present study, we identified that HIF1A-As2 and MYC form a double-regulatory loop that enhances cell survival, tumor growth and metastasis, suggesting targeting HIF1A-As2 could be a vulnerability in KRAS-dependent NSCLC." (PMID 37041291, 2023). "Interestingly, both PD‐L1 and CD47 are highly expressed in tumour cells and can be synchronously regulated by transcription factor MYC." (PMID 37974395, 2023). "Inhibition of MYC resulted in marked apoptosis and tumour regression." (PMID 36864508, 2023). "PD-L1 and CD47 are both highly expressed in tumor cells and can be simultaneously regulated by MYC." (PMID 37546397, 2023). "The fact that RUNX3 has the ability to regulate MYC at two different levels – through attenuation of Wnt signaling and MYC protein destabilization – may explain why RUNX3 functions as a potent tumor suppressor in the intestine and lung." (PMID 37400551, 2023). "Moreover, like CDK2, CDK4/CDK6 exert oncogenic roles in this tumor type, especially in MYC-amplified forms." (PMID 36839989, 2023). "However, we did not detect apparent differences to the other three samples in histological appearance and levels of MYC or SMARCA4 in this tumor." (PMID 37919824, 2023).
tumor (continued). "miR-138 can also inhibit MYC expression and suppress tumor growth of CRC and HCC cell lines." (PMID 37369946, 2023). "In the c-MYC/Mcl1 model, tumor nodules emerged from the liver around 3–4 weeks after HDTVi." (PMID 37040183, 2023). "The anti-tumor effects of APTO253 in AML were related to the inhibition of MYC." (PMID 37143070, 2023). "Thus, perturbations of direct MYC activity, or downstream effectors, such as miR-17/92 family members, can have potent effects on enhancing the tumor immune microenvironment and therapeutic benefit for this high-risk group of patients with OS." (PMID 37279073, 2023). "Furthermore, increasing evidence suggests that MYC hyperactivation can mediate tumor-induced immunosuppression at multiple levels." (PMID 36966168, 2023). "The inactivation of MYC in preclinical models might lead to sustained tumor regression due to oncogene addiction." (PMID 36959802, 2023). "AFP immunization synergizes with anti–PD-L1 to dramatically inhibit c-MYC/Mcl1 tumor progression." (PMID 37040183, 2023). "MYC analysis was done in cases with MYC expression ≥ 40% of the tumor cells." (PMID 36810796, 2023). "Consequently, OTUB1 increases c-MYC protein levels and the expression of c-MYC target genes including hexokinase-2, which increase glycolysis and tumor growth." (PMID 38264570, 2023). "Interestingly, intravenous administration of miR-138 significantly impedes MYC-driven tumor growth in vivo." (PMID 37369946, 2023). "Our findings could be explained as a feedback mechanism through which tumor cells adapt to MYC suppression and evolve to use alternative signaling pathways to support sustained proliferation." (PMID 36632215, 2023). "However, combined MYC overexpression and SMARCA4 loss successfully induced tumor formation in vivo after orthotopic transplantation in recipient mice." (PMID 37919824, 2023). "Importantly, the biological processes occurred in TME, such as angiogenesis, immune evasion, invasion, migration, and the recruition of stromal and tumor-infiltrating cells are under the modulation of c-MYC." (PMID 36721232, 2023). "We show that this signaling axis is operative across different types of human cancer and may affect additional tumor contexts given that SOX2 is expressed and implicated in at least 20 types of human cancer and MYC is deregulated in up to 70% of cancers." (PMID 35454854, 2022). "MYC contributes to the tumorigenesis of 70% of all neoplasms." (PMID 36499710, 2022). "To conclude, miR-34a-5p is anti-tumor in CRC through targeting c-MYC to control DNMT3 and PTEN." (PMID 34623601, 2022). "Previous studies have shown that MYC can bind directly to the promoter of PD-L1 gene, while PD-L1 can inhibit T cell responses in the tumor microenvironment, and further found that MYC inactivation in mouse tumors can down-regulate the expression of PD-L1 and enhance anti-tumor immune responses." (PMID 36582521, 2022). "Multiple oncogenes are involved in reprogramming glutamine metabolism to drive fast proliferation in tumor cells, including MYC which is known to upregulate the glutamine transporter SLC1A5 to increase the glutamine uptake, and the enzymes GLS1 / 2 which convert glutamine to glutamate." (PMID 35148308, 2022). "In addition, MYC can directly bind to the promoter of PD‐L1 gene, and MYC inactivation leads to reduced PD‐L1 mRNA and protein abundance in tumor cells, which in turn enhances the cellular anti‐tumor immune response." (PMID 34687270, 2022). "Indeed, the observed differences between MYC tumor cells and normal fetal PGCs are mainly based on chromatin remodeling and different expression of DNA and histone modifying genes." (PMID 35318328, 2022). "The development of more specific OGDH inhibitors may therefore be a desirable approach to therapeutic targeting of MYC-overexpressing tumours." (PMID 35945217, 2022).
tumor (continued). "Compared to normal colon tissue, cluster 2, 3, and 4 stage II CC tumours showed marked enrichment for MYC/E2F-dependent proliferation signatures (nominal p-value < 0.05) by GSEA analysis, without evidence of major biological differences beyond that (not shown)." (PMID 36612154, 2022). "Notably, the sole depletion of NK cells or CD8 T cells resulted in a CD226 dependent faster tumor progression in the VK*MYC MM model showing an ongoing attempt of immune control even under tumor progression." (PMID 34584204, 2022). "Indeed, the only ones with indisputable oncogenic functions are MYC and its paralogs, while the tumor facilitators CHREBP and MONDOA promote growth and proliferation without being directly oncogenic." (PMID 35203395, 2022). "Studies have shown that the small-molecule MYC inhibits tumor growth and enhances immunotherapy." (PMID 36510584, 2022). "MYC targets were positively correlated with tumor cellularity." (PMID 35370699, 2022). "Previous studies demonstrated that the MYC oncogene appears to play a role in immunogenicity by creating an environment of immune privilege for the tumors themselves, and MYC-targeted therapy induced tumor cell immunogenicity in stimulating host immunity." (PMID 36418292, 2022). "Interestingly, the MPA-induced tumors used in this study rely on ER/PR induction of the oncogene MYC to grow, with MYC inhibition resulting in cancer cell death and tumor regression." (PMID 35299741, 2022). "Whether MYC or other oncogenes regulate the production of tumor-specific ribosomes is yet to be determined." (PMID 35159381, 2022). "In contrast, most oncogenes are typically over-expressed in multiple tumor types, similar to MYC." (PMID 36038558, 2022). "MYC is an important proto‐oncogene that influences tumour development in many tumour types." (PMID 35170113, 2022). "In addition, fusions between MYC and IgH or IgL loci were found in 15% of treated and untreated MM tumor cells." (PMID 35053311, 2022). "In addition to known tumor-promoting genes, e.g., c-MYC, YAP1, RAD51B, TRIB3, SLC17A9, JADE1, we found that NAPRT, encoding a key enzyme for NAD+ biosynthesis from nicotinic acid, was also suppressed in HCC cells by the BRD4 inhibitor." (PMID 35399501, 2022). "Interestingly, more MYC 3′UTR shortening was observed in the tumor samples than in the adjacent normal samples, and in patients with cancer at the regional lymph nodes (N stage > 0)." (PMID 34937878, 2022). "The abnormal expression of TEAD could modulate several cancer-associated genes, including MYC, KRAS, NF2, BRAF and LKB1, which had crucial roles in the regulation of tumor immunity." (PMID 35077390, 2022). "Reassuringly, Eif4e, another MYC target gene, was also upregulated in Myc-R26Met tumours." (PMID 36433941, 2022). "In accordance with what we have reported in vitro results, miR-19 inhibition and c-MYC inhibition could reject tumor growth in nude mice." (PMID 35915613, 2022). "This is indicative of MYC dependence exclusively in aggressive tumor cell lines." (PMID 36860495, 2022). "Also, the percentages of MYC-positive tumor cells were significantly higher in tuft cell-like than non-tuft cell-like NECs (P < 0.001), but not between tuft cell-like and non-tuft cell-like SQCCs (P = 0.80)." (PMID 36402755, 2022). "Considering that c-MYC is a potent survival factor in cancer cells, our findings may provide new therapeutic approaches that target the tumor microenvironment, often characterized by hypoxia and nutrient deprivation." (PMID 35642054, 2022). "Notably, Cho S.W and colleagues showed that the promoter of lncPVT1 acts as a tumor suppressor DNA boundary element thus finely tuning the expression of c-MYC." (PMID 35090471, 2022).